C3 (complement C3)
Diseases named in the same sentence as C3 in open-access papers (continued):
Sharing a sentence is not in itself a finding about the gene and the disease.
C3 glomerulopathy (continued). "Only low serum C3 was more frequent in the group of C3 glomerulopathy (p: 0.056)." (PMID 34046124, 2021). "C3 glomerulopathy is an umbrella term describing a group of related forms of glomerulonephritis, and dense deposit diseases, defined by dominant or exclusive glomerular C3 deposition usually detected by immunofluorescence or immunohistochemistry." (PMID 34613485, 2021). "Generally, dominant C3 staining is more consistent with C3 glomerulopathy (C3G)." (PMID 28280937, 2018). "Rational treatment of C3 glomerulopathy would involve inhibition of C3 activation and there are a number of drugs that are in pre-clinical development that may achieve that and allow a more targeted therapy in the future." (PMID 28357053, 2017). "Currently, C3 glomerulopathy is defined as a disease process due to abnormal control of complement activation, deposition, or degradation and characterized by predominant glomerular C3 deposition with electron-dense deposits." (PMID 26746693, 2016). "Besides C3Nef, additional autoantibodies against CFH, CFB and to the individual components of C3-convertase (C3b and factor B) have been described in C3 glomerulopathies." (PMID 23227086, 2012). "In TMA, especially in aHUS, and C3 glomerulopathy, genetic sequencing studies have contributed to the identification of genetic variants involved in the complement pathways, such as: CFH, CFI, MCP/CD46, complement factor B (CFB), thrombomodulin (THBD), C3 and others." (PMID 39780910, 2024). "The procedure indicated the presence of membranoproliferative glomerulonephritis (MPGN) with predominant C3 complexes and limited immunoglobulin deposits, indicative of C3 glomerulopathy (C3G)." (PMID 37493956, 2024). "C3 Glomerulopathy (C3G) and Immune Complex-Mediated Membranoproliferative glomerulonephritis (IC-MPGN) are rare diseases characterized by glomerular deposition of C3 caused by dysregulation of the alternative pathway (AP) of complement." (PMID 34211499, 2021). "C3 glomerulopathy (C3G) is a recently defined heterogeneous group of glomerular diseases characterized by C3 dominant deposition on immunofluorescent staining, exclusion of post-infectious glomerulonephritis, and other well-defined renal diseases." (PMID 34658305, 2021). "C3GN is one of the two renal lesions covered by the more inclusive term C3 glomerulopathy (C3G), featured by proliferative glomerulonephritis under light microscopy and predominant C3 deposit under immunofluorescent microscopy." (PMID 34658305, 2021). "C3 glomerulopathy (C3G) is a complement-mediated renal disorder characterized by abnormal amounts of C3 within glomeruli." (PMID 33129896, 2021). "The recurrence of membranoproliferative glomerulonephritis associated with polyclonal immunoglobulin deposits in the kidney allograft is less common as compared to C3 glomerulopathy, and the lack of C3 or C4d deposits is associated with lower rate of recurrence." (PMID 34064132, 2021). "However, a second biopsy within 2 months showed more C3 deposition and suggested that the child might develop C3 glomerulopathy over time." (PMID 34177949, 2021). "In Cfh−/− mice (a model of C3 glomerulopathy, a kidney disease caused by the AP dysregulation), the ablation of C5 improves survival and reduces glomerular inflammation (mediated by C5a), but does not reduce proteinuria or glomerular C3 staining." (PMID 27199983, 2016). "Danicopan (NCT05162066), iptacopan (NCT04817618, NCT05755386) and Pegcetacoplan (NCT04729062) targeting Factor D, Factor B, and C3 respectively, have shown promise in PNH but are being trialed for diseases like C3 glomerulopathy and IgA nephropathy." (PMID 38895123, 2024). "C3 glomerulopathy encompasses a group of glomerular diseases characterized by the predominant deposition of complement component C3 on kidney biopsy without significant immunoglobulin staining." (PMID 40342409, 2025).
C3 glomerulopathy (continued). "C3 glomerulopathy comprises a group of glomerular diseases characterized by predominant complement component C3 deposition on kidney biopsy without evidence of significant immunoglobulin staining." (PMID 40342409, 2025). "Although C3-dominant immunofluorescence is characteristic of C3 glomerulopathy, it is not pathognomonic and must be interpreted in the appropriate clinical context." (PMID 41230477, 2025). "The identification of complement C1q and/or C3 proteins might suggest MGRS-related lesions such as PGNMIDs, immunotactoid glomerulonephritis, cryoglobulinemia glomerulonephritis, C3 glomerulopathy, or heavy chain and light chain deposition diseases." (PMID 39133392, 2024). "Cases with sole C3 deposition were not included in the study (excluding C3 glomerulopathy (DDD or C3GN))." (PMID 36211394, 2022). "C3 glomerulopathy (C3G) is a recent disease classification that is characterized by the presence of glomerular deposits (composed of C3) in the absence of significant amounts of immunoglobulin (Ig)." (PMID 33882866, 2021). "C5 blockade protected C3KI mice from disease, and through long-term studies of C5 genetic deletion, we have shown that while increased C3 turnover continues through dysregulation of the alternative pathway, this does not evolve into a C3 glomerulopathy." (PMID 30714990, 2019). "The C3 fragment deposition in C3KI.C5KO mice did not appear to lead to morphological features of C3 glomerulopathy, as glomeruli appeared normal in the Martius scarlet blue– (MSB-) and PAS-stained sections." (PMID 30714990, 2019). "C3 glomerulopathy is a recently defined umbrella classification for severe renal diseases that are characterized by C3 accumulation in the glomeruli without or with sparse immunoglobulin (Ig) deposition." (PMID 29670616, 2018). "In the case of C3 glomerulopathy, C3 deposition occurs in the glomeruli without immunoglobulin deposition." (PMID 30135690, 2018). "Notwithstanding some common pathogenetic associations, atypical hemolytic uremic syndrome (aHUS) is not considered a C3 glomerulopathy because endothelial injury usually is seen without significant C3 deposition or electron-dense deposits." (PMID 24161036, 2013). "C3 glomerulopathy (C3GP) which included Dense Deposit Disease (DDD) and C3 glomerulonephritis(C3GN) depending on the location of electronic density is a rare disease characterized by predominant C3 deposition in glomeruli and membranoproliferation in glomeruli." (PMID 34149444, 2021). "Also, the presence of glomerular C3 and lack of immunoglobulins qualifies the process as a C3 glomerulopathy." (PMID 28210641, 2017). "The term C3 glomerulopathy is recently defined by the pathological findings of complement 3 (C3) which is deposited within the glomerulus in the absence of substantial immunoglobulin, and there may remain much room for discussion." (PMID 25506445, 2014). "Because postinfectious GN typically is characterized by a reversible decrease in serum C3 and the presence of glomerular C3 without Ig, differentiation from C3 glomerulopathy sometimes may be possible only with knowledge of the clinical course." (PMID 24161036, 2013). "Hence, immunoglobulin-negative but C3-positive MPGN is newly referred to as C3 glomerulopathy." (PMID 23227086, 2012). "C3 glomerulopathy (C3G) is a recent disease classification that is characterized by the presence of glomerular deposits (composed of C3) in the absence of significant amounts of immunoglobulin and comprises dense deposit disease and C3 glomerulonephritis (C3GN)." (PMID 33882866, 2021). "The morphological phenotypic aspects of C3 glomerulopathy may be either those of DDD, characterized by dense osmiophilic deposits, or those of C3 glomerulonephritis (C3GN), which isolated deposits of C3 with absent or scanty deposits of immunoglobulins." (PMID 38076230, 2023).
C3 glomerulopathy (continued). "The newly emerged C3 glomerulopathy designation describes the MPGN type microscopic image with isolated C3 deposits, encompassing dense deposit disease and some formerly classified MPGN I and III cases with C3 deposits without clear staining for immune complexes." (PMID 24030732, 2014).
Hypertension (85 papers, 2009 to 2025). The presence of chronic increased pressure in the systemic arterial system. "Elevated plasma C3 levels are associated with hypertension, obesity, dyslipidemia, and increased risk of myocardial infarction." (PMID 41187099, 2025). "Clinical studies have consistently linked complement C3 dysregulation to the development and progression of hypertension." (PMID 41187099, 2025). "The diagnosis of APSGN is usually not difficult when a classical clinical nephritis presentation (haematuria, oedema, oliguria, and hypertension) is associated with serologic evidence of recent streptococcal infection and depressed serum C3 concentration." (PMID 38170231, 2024). "Complement C3 is a potential predictor of cardiovascular events; elevated C3 levels have been closely linked to insulin resistance, abdominal obesity, and hypertension." (PMID 36232862, 2022). "In the present study, we found a positive association between hypertension duration and serum C3 levels." (PMID 35433725, 2022). "In a population-based longitudinal study, plasma C3 levels were found to be associated with future blood pressure increases and the development of hypertension." (PMID 35433725, 2022). "Although age and glomerular loss cannot be modified, it is possible to correct hypertension, hypertriglyceridemia, hyperuricemia, high serum IgA and C4 levels, and a high serum IgA/C3 ratio." (PMID 31810207, 2019). "A patient aged 17 with dense deposit disease associated with complement activation, circulating C3 Nef, and Factor H mutation presented with nephrotic syndrome and hypertension." (PMID 24672732, 2014). "Elevated levels of circulating complement component 3 (C3), which plays a central role in the innate immune system, has been associated with increased risk of hypertension, metabolic syndrome, type 2 diabetes, and cardiovascular diseases." (PMID 22848687, 2012). "For example, elevated levels of serum complement C3, a central protein in the complement system, have been linked to rheumatoid arthritis, spondylarthritis, and cardiometabolic risk factors such as obesity, insulin resistance, and hypertension." (PMID 41393951, 2025). "Beyond blood pressure elevation, C3 dysregulation is also associated with hypertension-related comorbidities such as metabolic syndrome, type 2 diabetes, and atherosclerosis, further highlighting its pathogenic relevance across cardiovascular and metabolic axis." (PMID 41187099, 2025). "Importantly, multivariate analysis confirmed elevated C3 as an independent risk factor for both hypertension and hypertensive renal injury." (PMID 41187099, 2025). "Moreover, DisGeNET analysis results demonstrated remarkable changes were caused by SLC39A1 in genes associated with complement Factor I (C3 inactivator) deficiency, ischemic stroke, choriocarcinoma and hypertensive disease." (PMID 36407113, 2022). "Univariate analysis showed that, among the various clinical factors tested, tonsillectomy demonstrated a significant association with a reduced risk of recurrence, whereas hypertension, renal dysfunction and IgA/C3 ratio showed significant associations with an increased risk of recurrence." (PMID 26415960, 2016). "In summary, complement C3 acts as a central mediator in hypertension by linking immune activation, vascular remodeling, and RAS dysregulation." (PMID 41187099, 2025). "It emphasizes the importance of recognizing APIGN's clinical features, such as swelling of face and limbs, hypertension, and hematuria, supported by diagnostic markers like raised ASO titers and low serum C3 levels." (PMID 39356841, 2024). "The relationship between C3 and pathological conditions has been reported within the relationship between serum C3 levels and cardiometabolic diseases, such as hypertension, atherosclerosis and fatty liver." (PMID 38279167, 2024). "C3 protein glycosylation exhibited several changes in T1D complications, as well as in hypertension accompanying this condition." (PMID 37293493, 2023).
Hypertension (continued). "Of note, serum C3 levels were positively correlated with hypertension duration (r = 0.405, p = 0.008) and BMI (r = 0.449, p = 0.003)." (PMID 35433725, 2022). "It is thought that TWIST1 upregulates C3 to induce the EMT phenomenon that activates the intrarenal renin-angiotensin system and is associated the pathogenesis of hypertension." (PMID 36018840, 2022). "Elevated serum C3 and C5 levels in hypertensive patients and animal models of hypertension provide another hint of the role of the complement system in the etiology of hypertension." (PMID 35354938, 2022). "Age, sex, chronic tonsillitis, hypertension, proteinuria, eGFR, serum IgA, serum C3, serum C4, Oxford classification, glomerulosclerosis, RASI and immunosuppressants." (PMID 35156903, 2022). "The time from onset to biopsy, the prevalence of hypertension and hematuria, the level of serum triglyceride, serum IgG, serum C3 and serum C4 were comparable between these two groups." (PMID 36496400, 2022). "Even after adjusting for age, gender, hypertension, GBM, eGFR, KRT at onset, and crescents, C3 levels remained significantly associated with kidney survival." (PMID 35874697, 2022). "The complement proteins C1q and C3 have been detected in the CP in systemic hypertension, hepatosplenic schistosomiasis and liver cirrhosis." (PMID 34425919, 2021). "Diagnosis was suspected based on presence of clinical features such as hypertension, proteinuria, and nephrotic/nephritic syndrome, possibly combined with low serum C3." (PMID 29670616, 2018). "On the other hand, C3-mediated over-activation of the complement system was shown to induce hypertension following placental ischemia in rats." (PMID 28611769, 2017). "Additionally, after 42 days of MZXD treatment, levels of complement factors C3, C4, and immunoglobulins IgG, IgM, and IgA in the plasma of patients with phlegm-dampness type Stage I hypertension were significantly reduced (p < 0.05)." (PMID 40606611, 2025). "The diagnostic approach followed a structured clinical progression: the patient presented with generalized edema, uncontrolled hypertension, and frothy urine, prompting initial labs that revealed nephrotic-range proteinuria (5.2 g/day), hypoalbuminemia, and low complement levels (C3 and C4)." (PMID 40666590, 2025). "In disease-specific contexts, we delineate how C3 contributes to the pathogenesis of atherosclerosis, coronary artery disease, aortic aneurysm and dissection, hypertension, pulmonary arterial hypertension, peripheral vascular disease, stroke, and autoimmune- associated vasculitides." (PMID 41187099, 2025). "However, hematuria, severe proteinuria, hypertension, and low C3 complement levels are common in both diseases." (PMID 38076230, 2023). "In this patient presenting with purpura, swollen hands, abdominal pain, nephrotic range proteinuria, hypertension, and low serum C3 level, a renal biopsy demonstrated a membranoproliferative pattern of glomerular injury with co-dominant immunofluorescence of C3 and IgA." (PMID 35757129, 2022). "Compared with the non-IgAN group patients in the training cohort, the IgAN group patients were significantly younger on average, had a higher incidence of hematuria and hypertension, and had higher levels of serum albumin, urea nitrogen, creatinine, uric acid, IgA, IgG, and IgA/C3 ratios (P < 0.01)." (PMID 35585099, 2022). "In conclusion, our study found that patients with IgAN and histologic evidences of TMA had clinically worse kidney function, more hypertension and hematuria, greater proportions of low serum C3 at kidney biopsy, with a larger amount of individuals with endocapillary hypercellularity (E1)." (PMID 33147224, 2020). "Taken together, our data appear to indicate that hypertension causes the different altered expression of RBP4, C3, ALBf, A1MG and A1AT in the rat serum and that the altered levels of the two latter proteins were apparently normalized when the rats were treated with captopril." (PMID 22416803, 2012).
Hypertension (continued). "While C3a may act as a pro-inflammatory agent, several studies have shown that C3 (rather than C3a) is an important predictive factor for metabolic syndrome, insulin resistance and hypertension." (PMID 25856141, 2015). "In view of thrombocytopenia, accelerated hypertension, raised LDH levels, and background azotemia, complement levels were measured, which revealed depressed C3 levels and normal C4 levels." (PMID 39184759, 2024). "Moreover, our findings highlight specific clinical red flags, such as hypertension with proteinuria in anti-VEGF TMA and AKI with low serum C3 in ICI-related immune-mediated nephritis." (PMID 41290561, 2025). "Overall, the small decrease in Crry controlling the C3 convertase is not likely responsible for the ineffectiveness of sCR1 in altering hypertension or albuminuria with a high‐salt diet." (PMID 29595916, 2018). "Lack of hypertension and a normal C3 level were also not consistent with post-infectious glomerulonephritis." (PMID 27876011, 2016). "Although, in our study, hypertension (P=0.879), nephrotic range proteinuria (P=0.467), serum albumin levels (P=0.502), CRP (P=0.099), and reduced C3 level (P=0.453) were not considered as factors predicting RPGN." (PMID 41246678, 2025). "This showed that the relationship between these parameters was linear, rather than curved, after adjustment for age, hypertension, nuclear fragmentation, mesangial cell and matrix proliferation, microthrombi, ALB, serum C3, 24-hour proteinuria, endothelial hyperplasia, and Hb." (PMID 39719070, 2024).